ERBB3 (erb-b2 receptor tyrosine kinase 3)
Diseases named in the same sentence as ERBB3 in open-access papers (continued):
Sharing a sentence is not in itself a finding about the gene and the disease.
gastric cancer (continued). "Overexpression of ErbB3 was reported in human gastric cancer in several independent types of research, and also a high expression of ErbB3 was regarded as an indicator of poor prognosis in post-surgery patients." (PMID 28924391, 2017). "Our findings offer compelling evidence that APIP plays an essential role in ERBB3 signaling as a positive regulator for tumorigenesis, warranting future development of therapeutic strategies for ERBB3-driven gastric cancer." (PMID 26942872, 2016). "In the present study, we report an important function of APIP in ERBB2/ERBB3 signaling in gastric cancer." (PMID 26942872, 2016). "The increased expression of APIP in gastric cancer cells enhances the HRG-β1/ERBB3-induced activation of AKT and ERK1/2 which stimulate cell proliferation and positively increase tumorigenesis by elevating ELK-1, C-FOS or cyclin D1." (PMID 26942872, 2016). "Our study aimed to investigate the relationship between ERBB3 and ferroptosis in gastric cancer." (PMID 40846695, 2025). "HER3 is known to form a heterodimer with HER2 and may also contribute to treatment resistance, although the precise role of ERBB3 in gastric cancer remains to be investigated." (PMID 36612265, 2022). "Recent works have implied the role of ErbB3 in gastric cancer as a key signaling hub." (PMID 28924391, 2017). "Therefore, APIP can serve as a potential therapeutic target in gastric cancer, specifically targeting ERBB3 signaling in APIP-overexpressing cancers." (PMID 26942872, 2016). "ErbB4 mutations have been described to occur in lung, breast, gastric cancer and melanoma and like for ErbB3 differ from those observed in EGFR or HER2 by not displaying characteristic mutational hotspots." (PMID 24643470, 2014). "To this end we chose to examine the efficacy of the A5/F4 oligoclonal alone and in combination with trastuzumab using the NCI-N87 ERBB2+ gastric cancer xenograft model, as inhibiting ERBB3 in the setting of ERBB2+ gastric cancer represents a promising approach for the treatment of this disease." (PMID 25386657, 2014). "ERBB3 is widely known for its role in cancer as amplification of this gene and/or over-expression of its protein have been shown in numerous cancers, including prostate, bladder, gastric cancer, and breast tumors." (PMID 20668683, 2010). "Recent studies have identified oncogenic erbB3 gene mutations in colon and gastric cancers; however, overexpression without gene alteration is still the major mechanism for HER3 to be associated with a worse survival in patients with a wide variety of solid tumors." (PMID 30093840, 2018). "The gastric cancer genome is characterized by focal amplification of oncogenes, including receptor tyrosine kinases, such as ERBB2 (HER2), EGFR, ERBB3, VEGF-A, KRAS/NRAS, MET, JAK2, and PD-L1/PD-L2." (PMID 38733489, 2024). "The presence of neuromodulin, a ligand for ErbB3, leads to heterodimerization of ErbB2, ErbB3, and ErbB4, thereby reducing the cytotoxicity of T-DMI in gastric cancer cell lines." (PMID 37305567, 2023). "DARPP-32 has been shown to promote resistance of gastric cancer cells to EGFR inhibitors by promoting an interaction between EGFR and ERBB3, which drives PI3K/AKT signaling to “bypass” EGFR TKI resistance." (PMID 34675407, 2022). "On the other hand, cross-talk between ERBB and FGFR receptors has also been described, with ERBB3 required for the maintenance of FGFR2 phosphorylation and proliferation in some FGFR2-amplified gastric cancer cells." (PMID 35501832, 2022). "Accordingly, MET gene amplification predicted higher MPZL3 expression than cell lines without any RTK amplification and MPZL3 levels are positively correlated with MET and ERBB3 expression in LUSC and gastric carcinomas." (PMID 35249128, 2022). "EGFR, ERBB3/HER3, VEGF, PI3K/mTOR, FGFR2 and MET show promise as new targets for gastric cancer treatment." (PMID 29237412, 2017).
gastric cancer (continued). "Overall, these results suggest that APIP stimulates cell proliferation via ERBB3, acting in conjunction with ERBB2, in gastric cancer cells." (PMID 26942872, 2016). "R. J. Wang inhibited gastric cancer growth and metastasis in vitro, which may be related to the inhibition of the ERBB2/ERBB3/PI3K/AKT pathway." (PMID 39549017, 2024). "Although, there are various reports about the prognostic value of EGFR members separately in gastric cancer, there is not any report about the probable correlation between ErbB1 and ErbB3 co-expression and gastric cancer prognosis." (PMID 30621788, 2019). "Although there is not any report of ErbB3 or ErbB4 overexpression in gastric cancer, ErbB3 expression is frequently seen in advanced stages of gastric cancers and is correlated with poor prognosis." (PMID 30621788, 2019). "Apart from various reports about the prognostic value of EGFR members separately in gastric cancer, there is not any report about the probable correlation between ErbB1 and ErbB3 co-expression and gastric cancer prognosis." (PMID 30621788, 2019). "ErbB3 interacts prominently with the phosphoinositide-3-kinase (PI3K)/AKT pathway, and its overexpression has been reported in many primary cancers, including carcinomas of the stomach, colon, pancreas, oral cavity, breast, ovarian, prostate, and lung (." (PMID 31261874, 2019). "Assessment of ERBB3 expression in gastric cancer cell lines revealed high levels of phosphorylated ERBB3 (Y1289) in growing SNU-5 and SNU-16 cells but not in SNU-620 cells." (PMID 26942872, 2016). "More recently it has been reported that, in human MKN7 gastric cancer cells, HRGβ1 can also circumvent the antiproliferative action of the selective EGFR-TKI CGP59326 through promotion of erbB3/erbB2 heterodimerization and activation of the PI3K signalling pathway." (PMID 17686159, 2007). "Finally, this study indicated that the G/T SNP might serve as a tumor promoter and poor prognosis indicator in gastric cancer by affecting the binding of miR-204 and miR-211 on the 3’ UTR of ErbB3." (PMID 35330456, 2022). "In summary, this is the first report showing that APIP displays a pivotal oncogenic activity by binding to ERBB3 to stimulate the formation of ERBB3/ERBB2 heterodimer, leading to amplification of HRG-mediated signaling involved in cell proliferation and tumorigenesis in gastric cancer." (PMID 26942872, 2016). "A few genes, such as the receptor tyrosine-protein kinase erbB-3 (ERBB3), which is related to growth factors, and dual specificity protein kinase (TTK), which is related to cell proliferation, were found to be up-regulated in the intestinal gastric cancer samples." (PMID 21435268, 2011). "There are several known non-ERBB regulators of ERBB3, such as MET, BRK, EBP-1 and CDK5, in gastric cancer." (PMID 26942872, 2016).
ovarian carcinoma (102 papers, 2006 to 2026). A malignant neoplasm originating from the surface ovarian epithelium. "Insulin-Like Growth Factor Receptor 1 (IGF-1R) and Epidermal Growth Factor Receptor 3 (ErbB3) have been implicated as two such drivers of resistance, however their simultaneous role in ovarian cancer chemotherapy resistance remains poorly elucidated." (PMID 31728045, 2019). "Clinical use of pertuzumab has revealed a role for ErbB3, in that low levels of ErbB3 expression are associated with patient responses in ovarian cancer." (PMID 23202898, 2012). "Another potentially relevant circuit for tumorigenesis, in particular for ovarian cancer, a leading cause of death from gynecologic malignancies, is composed of HoxA4, miR-125b and ERBB3." (PMID 20731828, 2010). "Moreover, tissue analysis from ovarian cancer patients indicated an association of ErbB3 or HRG expression with decreased patient survival." (PMID 31728045, 2019). "Moreover, elevated levels of ERBB3 are associated with poor outcomes in ovarian cancer patients." (PMID 35761259, 2022). "In the ovarian cancer study, we observed that the expression levels of ERBB3 and MUC1 were higher in mucinous and clear cell carcinoma than in serous and endometrioid carcinoma." (PMID 40046734, 2025). "For example, seribantumab (MM-121), a neutralizing mAb against ErbB3, significantly reduced tumor growth in xenograft models of lung and ovarian cancer derived from patients with carcinogenic neuregulin 1 (NRG1) fusion." (PMID 36293051, 2022). "Activating the ligands of both IGF-1R and ErbB3 promotes ovarian cancer cell proliferation and pro-survival signaling activation, whereas the dual blocking of IGF-1R and ErbB3 enhances the efficacy of relevant chemotherapies." (PMID 36142299, 2022). "miR-152 was shown to suppress the proliferation, and metastatis abilities of ovarian cancer cells by suppressing the ERBB3 expression in ovarian cancer cell strains." (PMID 34629107, 2021). "Most importantly, a role for ERBB3 has been described in promoting chemoresistance and tumor progression in ovarian cancer." (PMID 31164954, 2019). "Our data indicate a potential benefit of dual IGF-1R/ErbB3 inhibition for ovarian cancer treatment, and highlight the potential impact of istiratumab in combination with standard of care chemotherapy to treat ovarian cancer." (PMID 31728045, 2019). "The aim of this work is to determine the effects of dual IGF-1R/ErbB3 inhibition on ovarian cancer cell signaling, growth, and in vivo efficacy." (PMID 31728045, 2019). "Screening in ovarian cancer cells using lentivirally-delivered short hairpin RNA library targeting RTKs revealed ErbB3 as a relevant target and both genetic and pharmacological inhibition of the HRG/ErbB3 axis activation resulted in tumor growth inhibition." (PMID 31728045, 2019). "Our results suggest a role for IGF-1R and ErbB3 in driving chemotherapy resistance of ovarian cancer." (PMID 31728045, 2019). "Activating ligands of both IGF-1R and ErbB3 promote ovarian cancer cell proliferation and pro-survival signaling activation, whereas dual blocking of IGF-1R and ErbB3 enhances the efficacy of relevant chemotherapies." (PMID 31728045, 2019). "Here we show that IGF-1R, ErbB3 and their ligands are expressed in a significant proportion of ovarian cancer patient samples." (PMID 31728045, 2019). "Elevated levels of Human Epidermal Growth Factor Receptor 3 (ErbB3/HER3) in ovarian cancer cells and Neuregulin 1 (NRG1) in the omentum allowed for tumor cell localization and growth in the omentum." (PMID 29389895, 2018). "One of the studies from our collaborators using microfluidics-based isolation of tumor cells by targeting ERBB3 protein from blood samples of a parabiosis model of ovarian cancer was able to capture more than 90% of CTCs in the blood samples." (PMID 29321816, 2017).
ovarian carcinoma (continued). "Using a parabiosis model, we and our collaborators have demonstrated that ovarian cancer cells expressing high levels of human ERBB3 can metastasize hematogenously to the omentum." (PMID 29321816, 2017). "In late-stage ovarian cancer patients, approximately 30% of primary tumor cells derived from malignant ascites fluid show constitutive active p-ErbB3, which is inhibited by seribantumab." (PMID 28725482, 2017). "In conjunction with the studies, which demonstrate the role of ERBB3 on metastasis of ovarian cancer, another study using immunohistochemical analysis identified that high levels of ERBB3 are associated with poor outcome in ovarian cancer patients." (PMID 29321816, 2017). "Studies using parabiosis mouse models showed that more than 95% of CTCs collected from mice bearing ovarian tumors and 90% of CTCs from ovarian cancer patients are ERBB3 positive." (PMID 29321816, 2017). "Consistent with a role of ERBB4 as heterodimerizing partner, tyrosine phosphorylation of ERBB3 was widely detectable in ovarian cancer samples." (PMID 26745281, 2016). "Activation of AKT by Dox has been linked to the presence of human epidermal growth factor receptor 3 (HER3, ERBB3 ) in ovarian cancer and was attenuated by the addition of tyrosine kinase inhibitors lapatinib and/or erlotinib." (PMID 26597249, 2015). "Several anti-ErbB3 monoclonal antibodies are under development and have been brought to clinical trials for a variety of indications such as breast, colorectal and ovarian cancers, given the known role of ErbB3 in resistance to therapy." (PMID 26208478, 2015). "Our previous study showed that miR-199a inhibits tumor angiogenesis by targeting ERBB2 and ERBB3 thus suppressing their downstream VEGF in ovarian cancer cells." (PMID 24413338, 2014). "Increased secretion of HRG has been found in a subset of ovarian cancers, and thereby stimulates ovarian cancer cell proliferation via erbB3/HRG autocrine loop." (PMID 24886126, 2014). "It has been reported that ErbB3 mRNA expression, as detected by RT-PCR, is increased in a proportion of ovarian cancers." (PMID 22889873, 2012). "Signaling activation by ErbB3 in ovarian cancers seems to depend in some cases upon the formation of heterodimers with HER2 while in others, the activation of ErbB3 is independent of heterodimers with HER2 or EGFR." (PMID 22889873, 2012). "Amplifications and overexpression of various EGFR family members, including EGFR, Her2, and ErbB3, have been reported in epithelial ovarian cancer." (PMID 21364581, 2011). "Moreover, we observed the downregulation and copy number deletion of two genes (ERBB3 and HMGA1) in the NR group, which are associated with poor prognosis and tumorigenesis in ovarian cancer." (PMID 39135097, 2024). "miR-152 promoted apoptosis of ovarian cancer cells through repression of ERBB3 expression." (PMID 36445489, 2023). "ERBB3 activates PI3K by promoting EMT in ovarian cancer cells." (PMID 35761259, 2022). "An anti-ERBB3 antibody led to tumour regression in an ovarian cancer-derived xenograft model, suggesting that the selective inhibition of ERBB3 may exert more potent antitumour effects than pan-ERBB inhibitors." (PMID 33008426, 2020). "Increasing evidence in recent years suggests a distinct role for ErbB3 signaling in ovarian cancer." (PMID 31728045, 2019). "In summary, our results suggest that the interplay between IGF-1R and ErbB3 may serve as a regulator of tumor growth and resistance to chemotherapies in ovarian cancer." (PMID 31728045, 2019). "Consistent with the findings that ERBB3 promotes hematogenous metastasis of ovarian cancer, depletion of ERBB3 by siRNA or treatment with ERBB3-specific monoclonal antibodies reduced the formation of CTCs and the incidence of hematogenous metastasis of ovarian cancer in mouse models." (PMID 29321816, 2017). "Also, downregulation of miR-199a resulted in high expression of ERBB2 and ERBB3 in ovarian cancer cells and promoted cancer progression." (PMID 28978024, 2017).
ovarian carcinoma (continued). "Furthermore, ERBB3 levels positively correlate with total tumor burden and overall survival of ovarian cancer patients." (PMID 29321816, 2017). "Although these experiments show that HRG/ErbB3 signaling has the ability to render ovarian cancer cells insensitive to paclitaxel, the question remains whether or not cancer cells invoke this mechanism to adapt to the stress of cytotoxic therapy." (PMID 28725482, 2017). "In serous ovarian cancer, the ERBB4 CYT-1 variant we expressed in Ba/F3 cells was identified as independent prognostic factor for survival, and may cooperate with NRG1 autocrine signaling to support ERBB3-mediated ovarian cancer cell proliferation in vivo." (PMID 26745281, 2016). "Recent studies suggest that erbB3 signaling also contributes to chemoresistance in ovarian cancer, as the chemotherapeutic drug doxorubicin upregulates erbB3 ligands to activate the erbB3/PI-3 K/Akt signaling in ovarian cancer cells." (PMID 24886126, 2014). "Interestingly, four alternate c-ErbB3 transcripts (1.6, 1.7, 2.1 and 2.3 kb) were isolated from an ovarian carcinoma-derived cell line." (PMID 22889873, 2012). "ErbB3 has been reported to be amplified and overexpressed in epithelial ovarian cancers." (PMID 21364581, 2011). "In a mouse model of human ovarian cancer, depletion of ErbB3 by RNAi reduced tumour growth and prolonged mouse survival, while treatment with a monoclonal anti-ErbB3 antibody (MM-121, Merrimack Pharmaceuticals, Cambridge, MA, USA) also resulted in inhibition of tumour progression." (PMID 21364581, 2011). "Recent reports have suggested that members of the EGFR family, such as ErbB3, may have a role in supporting the growth and proliferation of human ovarian cancer cells." (PMID 21364581, 2011). "The identification of an miRNA, i.e. miR-125b, that could downregulate ERBB3 would be very valuable for ovarian cancer treatments." (PMID 20731828, 2010). "Also, ERBB3, which was deleted in the immune region of the NR group, is known to be an oncogene, and its overexpression is correlated with the poor prognosis of patients with ovarian cancer." (PMID 39135097, 2024). "Interestingly, ERBB3 is involved in the progression and metastasis of ovarian cancer." (PMID 36620547, 2022). "Therefore, the Gab2 acted as ErbB3, which is important in ovarian cancer." (PMID 26095858, 2015). "MM-121 is an erbB3-blocking Ab that is being actively investigated in clinical trials of cancer patients with solid tumors, such as advanced non-small cell lung cancer, colorectal cancer, squamous cell head and neck cancer, and platinum resistant/refractory ovarian cancer." (PMID 24168763, 2013). "Of the ovarian carcinomas, 16% of the tumors overexpressed ErbB3 protein compared to normal ovarian; moreover expression of NRG was detected in the majority of ovarian carcinomas and cell lines and this could be a potential for autocrine regulation of cell growth." (PMID 22889873, 2012). "Furthermore, in a subset of ovarian cancer cells that display an NRG1-expressing/phosphorylated-ErbB3 phenotype, depletion of ErbB3 by RNA interference (RNAi) could result in anti-proliferative effects in vitro." (PMID 21364581, 2011). "In ovarian cancer, NUF2 contributed to tumor initiation and development through PI3K-AKT and MAPK signaling axes mediated by ERBB3." (PMID 39242581, 2024). "In ovarian cancers, increase of the neuregulin 1 (NRG1)/Erb-B2 receptor tyrosine kinase 3 (ERBB3) pathway has been found to contribute to SINE resistance." (PMID 39050883, 2024). "Expression of NRG1 and ERBB3, as well as NRG1 secretion, were increased in SINE-resistant ovarian cancer cells." (PMID 39050883, 2024). "Among the DEGs, ERBB3 overlapped in the PI3K/AKT and MAPK signaling pathways, which is involved in the progression and metastasis of ovarian cancer and many other cancers." (PMID 36620547, 2022). "A survey of ovarian cancer patient samples was performed for IGF-1R, ErbB3, and their respective ligands." (PMID 31728045, 2019).